GPX1 (glutathione peroxidase 1)
Diseases named in the same sentence as GPX1 in open-access papers (continued):
Sharing a sentence is not in itself a finding about the gene and the disease.
type 2 diabetes (14 papers, 2007 to 2025). "The symptoms of type 2 diabetes were found to be relieved in GPX1 knockout and dietary selenium-deficient mice." (PMID 37238669, 2023). "In a small Japanese study of 173 type 2 diabetes patients, the Pro198Leu polymorphism in Gpx1 gene was found to be a predisposing factor in distal symmetric polyneuropathy and macrovascular disease." (PMID 27592002, 2017). "The purpose of the present study was to evaluate the association of the Pro197Leu polymorphism in the Gpx1 gene with diabetic neuropathy in type 2 diabetes patients." (PMID 27592002, 2017). "In the present study, we identified an association between the Pro197Leu polymorphism in the Gpx1 gene and diabetic peripheral neuropathy in type 2 diabetes patients." (PMID 27592002, 2017). "The potential of selenoproteins such as selenium-containing GPxs (GPx1–4 and 6) to protect against oxidative stress led to the expectation that selenium would also be protective against type 2 diabetes and other cardiovascular risk factors." (PMID 25269026, 2014). "Some studies reported an association with Pro198Leu polymorphism in Gpx1 with type 2 diabetes." (PMID 27592002, 2017). "Reductive stress due to GPX1 overexpression can result in adverse health consequences such as type-2 diabetes." (PMID 27404728, 2016). "However, selenoproteins are generally considered beneficial for health, although GPx1 is implicated in insulin resistance (IR) and SELENOP is associated with type 2 diabetes mellitus (T2DM)." (PMID 34207090, 2021). "The finding that GPx-1 expression is essential for EPC functions may also have clinical implications, given that patients with chronic heart failure and with type 2 diabetes showed a downregulation of GPx-1." (PMID 20066135, 2008).
Hyperinsulinemia (13 papers, 2010 to 2024). An increased concentration of insulin in the blood. "The primary reason for this phenotype is attributed to the unexplainable Gpx1 overexpression in the pancreas (about 20 times), as compared to other tissues, and is associated with the increased function of insulin synthesis and secretion machineries consequently resulting in hyperinsulinemia." (PMID 37107221, 2023). "Previously we showed that GPX1 transgenic-overexpressing (OE) mice develop hyperglycemia, hyperinsulinemia, insulin resistance and obesity." (PMID 37107221, 2023). "Diet restriction alleviated all metabolic symptoms except hyperinsulinemia, suggesting the functional role of GPx1 lies in regulating insulin production." (PMID 26861388, 2016). "Overexpression of GPx1 in mice yielded surprising results, leading to reduced glucose clearance, hyperinsulinemia, hyperglycemia, and diminished insulin signaling." (PMID 26861388, 2016). "It has been found that high dietary selenium intake may result in impaired insulin sensitivity as well as overexpression of GPx1 leading to dysregulated insulin secretion and hyperinsulinemia." (PMID 38877419, 2024). "Interestingly, over-production of selenium-dependent glutathione peroxidase-1 can induce hyperinsulinemia in mice." (PMID 20459618, 2010). "Paradoxically, overexpression of Gpx1 in mice induced a type 2 diabetes-like phenotype, featuring augmented glucose-stimulated insulin secretion (GSIS) and chronic hyperinsulinemia." (PMID 37107224, 2023).
colorectal cancer (12 papers, 2016 to 2023). A primary or metastatic malignant neoplasm that affects the colon or rectum. "In this place, it should also be noted a that Gpx-1 Pro198Leu polymorphism has been extensively studied in breast, leukaemia, and colorectal cancer." (PMID 37242524, 2023). "The GPX1 rs1050450 minor homozygous genotype has been implicated in reduced skin antioxidative capacity and was found to be related to various breast, lung, prostate, and colorectal cancers." (PMID 37763073, 2023). "Antioxidant activities and protection against colorectal cancer (promoted the gene expression of GPx-1 and GPx-2 and enzyme activity of GPx-1 in rat colon)." (PMID 38202719, 2023). "Similar to GPx1, unusual expression of GPx2 is also observed in different tumors; for example, GPx2 is overexpressed in colorectal cancer, whereas a lower expression of GPx2 is detected in prostate intraepithelial neoplasia." (PMID 38202704, 2023). "This is in line with in vitro studies where overexpressed HIF-1α in colorectal cancer cells resulted in enhanced GPx1 expression through TGF-βRI/Smad2/ERK1/2/HIF-1α signalling cascade, suggesting transcriptional regulation of GPx1 by HIF-1α." (PMID 27656047, 2016). "However, data on the clinical application of Gpx-1 expression in European colorectal cancer patients, especially colorectal adenocarcinoma, are scarce." (PMID 37242524, 2023). "In colorectal cancer cell DLD-1, transforming growth factor-β1 (TGF-β1) protects cancer cells from exogenous H2O2-induced oxidative damage and cell death by upregulating GPX1 protein expression and enzymatic activity." (PMID 35626163, 2022).
glioblastoma (12 papers, 2011 to 2025). The most malignant astrocytic tumor (WHO grade IV). "Moreover, an inverse association between GPx1 expression and temozolomide potency in two glioblastoma cell lines has recently been described; our results with the HAP-1 cell lines support this finding." (PMID 33353055, 2020). "Hypoxia increases the expression of exosomal GPx1, which assists glioblastoma and endothelial cells in countering H2O2 or radiation-induced apoptosis in vitro and in vivo." (PMID 41009025, 2025). "The depletion of GPx1 not only results in H2O2 overload but also inhibits the growth of glioblastoma xenografts, indicating that GPx1 is vital for tumor survival under hypoxic conditions." (PMID 41009025, 2025). "Clinical data demonstrates that GPX1 expression is positively correlated with tumor grade and inversely correlated with the overall survival outcome of glioblastoma patients." (PMID 40346054, 2025). "In hypoxic glioblastoma, GPX1 controls hydrogen peroxide balance and alleviates oxidative stress." (PMID 40346054, 2025). "GPx1 is essential for maintaining the balance of H2O2 in hypoxic glioblastoma." (PMID 41009025, 2025). "Similarly, HIF2α has been shown to regulate GPx1 to ensure resistance to oxidative stress and radiation, while contributing to glioblastoma progression via various mechanisms such as the DDX28-mediated regulation of eIF4E2-driven translation." (PMID 38893207, 2024). "Similarly, HIF2α contributes to glioblastoma progression by regulating genes such as GPx1, vasorin, beclin-1, and galectin-3, thereby influencing the response to oxidative stress, angiogenesis, autophagy, and cell survival." (PMID 38893207, 2024). "It has been shown to be overexpressed in many cases of glioblastoma multiforme (GBM) and is required for the correct splicing of the glutathione peroxidase 1 (GPX1) gene, which is required for full levels of tumor growth and invasion." (PMID 36979496, 2023). "Following 48 h of So exposure to A-172 glioblastoma cells, there was no significant change in the expression of genes encoding selenoproteins, and the level of genes encoding selenium-containing proteins GPX1, GPX4, TR1, and TR3 significantly increased." (PMID 36768736, 2023). "In glioblastoma (GBM), SELENOP maintains GPx1 and GPx4 levels, contributing to ferroptosis sensitivity and offering a potential target for overcoming drug resistance." (PMID 39942544, 2025). "When GPx1 is depleted, there is an overload of H2O2, leading to increased apoptosis in glioblastoma cells." (PMID 41009025, 2025). "Anti-oxidant genes such as CAT, SOD2, and GPX1 were not elevated in PAM- or PAL-treated glioblastoma cells." (PMID 31541175, 2019). "GPx1 expression was positively correlated with tumor grade, expression of HIF-1α (hypoxia-inducible factor-1α), HIF-1α target genes, and tetraspanin exosomal marker genes (CD9, CD63, CD81)-conversely, it was inversely correlated with the overall survival outcome in human glioblastoma specimens." (PMID 41009025, 2025). "In glioblastoma, NONO cooperates with PSPC1 to bind GPX1 pre-mRNA, regulating its alternative splicing and thereby influencing tumor growth, invasion, and redox homeostasis." (PMID 41174721, 2025). "In glioblastoma, NONO cooperatively binds to the intron region of GPX1 pre-mRNA with PSPC1, regulating the alternative splicing of GPX1, which affects tumor growth, invasion, and redox homeostasis." (PMID 41174721, 2025).
neuroblastoma (11 papers, 2015 to 2024). Neuroblastoma (NB) is the most common solid, extracranial childhood tumor. "The increase in survival and protection has been proven in a neuroblastoma cell line infected with a lentivirus vector carrying the coding sequence for human GPx1 pLV-GPX1." (PMID 35205224, 2022). "Our results also indicate that the pre-exposure of neuroblastoma cells to RF strongly limited the MD-dependent decrease in both gpx1/sod1 (0.72) and gpx1/sod2 (0.82) ratios." (PMID 30185877, 2018). "For example, inhibition of sodium nitroprusside-mediated NO release and increased production of transcripts coding for antioxidant enzymes (i.e., SOD1, GPx1 and CAT) have been reported upon melatonin treatment in neuroblastoma cells and HUVEC, respectively." (PMID 35883714, 2022). "We have addressed this issue using two experimental models, namely SY5Y neuroblastoma cells treated with buthionine sulfoximine (BSO), one of the most commonly used drug to induce oxidative stress, and Glutathione peroxidase 1 and 2 (GPx1/2) double-knockout mice." (PMID 26239807, 2015).
depression (10 papers, 2013 to 2025). "The recessive homozygous genotype of the GPX1 polymorphism rs1050450, together with greater anxiety and depression scores and the female gender, was revealed to be a significant predictor of more frequent waking-state oral behaviours." (PMID 37371925, 2023). "When substituted for depression, an increase in anxiety by one scalar point increased waking-state oral behaviour score by 0.721 scalar points, while female sex and GPX1 polymorphism remained significant." (PMID 37371925, 2023). "Next, a linear regression model was created to examine the gene-dose effect of GPX1 C versus T (CC = 2, CT = 1, TT = 0) alleles on depression scores (GDS total score)." (PMID 23289525, 2013). "Selenium was most strongly protective against depression among homozygous carriers of the C allele at the Pro198Leu polymorphism of the GPX1 gene." (PMID 23289525, 2013). "The current study was designed to (a) study the link between groundwater selenium levels and depressive symptoms, (b) determine if the Pro198Leu GPX1 directly impact depression risk, and (c) determine if the Pro198Leu polymorphisms of the GPX1 gene impact these findings." (PMID 23289525, 2013). "The AA genotype of rs1050450 (GPX1) as well as depression, anxiety, somatosensory amplification, hypervigilance, and sex were found to have a significant association with waking-state oral behaviours." (PMID 37371925, 2023). "In patients with depression and hypertension, there are decreased glutathione peroxidase-1 (GPx-1) and SOD-1 activities but increased concentrations of MDA and H2O2, in comparison with the controls." (PMID 32148646, 2019). "Interestingly, five TWAS significant genes (TMEM161B-AS1, GMPPB, STAU1, NDUFA2 and GPX1) were significantly upregulated in brains of depression cases compared with controls in GSE102556 dataset." (PMID 34021117, 2021). "Several TWAS significant genes were also dysregulated in brains of depression cases compared with controls (including PCDHA8, FANCL, TMEM161B-AS1, GMPPB, STAU1, NDUFA2, GPX1 and PCDHA7), implying that genetic variants may contribute to depression risk by regulating gene expression." (PMID 34021117, 2021). "However, to date, we are aware of no studies that have examined the impact of GPX1 polymorphisms on the selenium- depression link." (PMID 23289525, 2013). "This study shows the effects of chronic administration of agomelatine on expression and the methylation status of Sod1, Sod2, Gpx1, Gpx4, Cat, Nos1, and Nos2 in the brain stricture and blood in the chronic mild stress (CMS) animal model of depression." (PMID 32545212, 2020). "The most interesting finding in this study was higher PDIA3 expression and lower FGB, GPX-1, and RARB expression in patients with major depression than in healthy controls." (PMID 24383611, 2014). "The levels of fibrinogen beta chain (FIBB), fibrinogen gamma chain (FIBG), retinoic acid receptor beta (RARB), glutathione peroxidase 1 (GPX1), SH3 domain-containing protein 19 (SH319), and T-complex protein 1 subunit beta (TCPB) were lower in patients with major depression than in healthy controls." (PMID 24383611, 2014).
ischemia (10 papers, 2012 to 2024). A hypoperfusion of the BLOOD through an organ or tissue caused by a PATHOLOGIC CONSTRICTION or obstruction of its BLOOD VESSELS, or an absence of BLOOD CIRCULATION. "Other authors found that a GPx-1 deficiency exacerbates neurotoxicity in cortical neurons and increases infarct size in response to ischemia/reperfusion injury, respectively." (PMID 37761814, 2023). "Consistent with the decreased regenerative capacity of endothelial cells in the setting of the BAS model, earlier studies reported that GPx1 deficiency attenuated neovascularization in a hindlimb model of ischemia." (PMID 34579115, 2021). "GPx1-deficient mice also had a decrease in post-ischemia microvascular perfusion with increased vascular permeability and increased MMP9 expression." (PMID 34579115, 2021). "The attenuation of revascularization was due, in part, to decreased numbers of endothelial progenitor cells following ischemia and the enhanced sensitivity of GPx1-deficient progenitors to ROS-induced apoptosis." (PMID 34579115, 2021). "Consistent with this, cellular glutathione peroxidase, GPX1 has been implicated as having a critical neuroprotective role in many brain disease and injury models, including Parkinson’s disease, dementia and ischemia." (PMID 22701605, 2012). "GPX-1 and HO-1 are both essential antioxidants in the myocardial response to ischemia and function mechanistically as part of the Nrf2 pathway." (PMID 38391611, 2024). "Multiple pre-clinical studies have demonstrated that during myocardial injury produced by ischemia and the combination of ischemia and reperfusion, selenoproteins, predominantly glutathione peroxidase-1, reduce oxidant stress." (PMID 23434902, 2013). "Gene expression ratios of the antioxidant enzymes Gpx1, Sod1 and Sod2, Cat and Hmox1 were evaluated 24 hours after ischemia by means of qRT-PCR to determine whether increased antioxidative capacity might be involved in FXN-mediated neuroprotection." (PMID 29555919, 2018). "We have previously shown that mice lacking the gpx-1 gene are highly susceptible to oxidative-stress and have proposed that gpx-1 may be an attractive target for increasing the anti-oxidant capacity in ischemia/reperfusion brain injury and cigarette smoke-induced lung inflammation." (PMID 22412999, 2012). "Notably, Que/mAb GAP43-Exo attenuated oxidative stress-induced ischemia/reperfusion injury and induced the activation of the Nrf2/HO-1 pathway by promoting the nuclear translocation of Nrf2 and upregulating expressions of NQO-1, HO-1, SOD1 and GPx1." (PMID 34001136, 2021).
Parkinson disease (10 papers, 2011 to 2025). A progressive degenerative disorder of the central nervous system characterized by loss of dopamine producing neurons in the substantia nigra and the presence of Lewy bodies in the substantia nigra and locus coeruleus. "In our tissues, the relevance of GPX1 in terms of protein expression and the network hub fits with its role in contrasting ROS-mediated toxic effects, as already demonstrated in Parkinson’s and Alzheimer’s disease." (PMID 36899835, 2023). "GPX1 plays a significant neuroprotective role in various neurological disorders, such as Parkinson’s disease and cerebral ischemic stroke, through its antioxidant function." (PMID 33494071, 2021). "Peroxiredoxin 6 expression is also greatly increased in Parkinson’s disease substantia nigra, as is glutathione peroxidase 1 in cingulate gyrus and middle frontal gyrus (substantia nigra was not investigated)." (PMID 28820437, 2017). "GPx-1 positive microglia are increased in Parkinson's disease and dementia with Lewy bodies, and it has been proposed that GPx-1 can participate in a cellular process to enzymatically degrade concentric Lewy bodies." (PMID 21629698, 2011). "Associations of GPX1 polymorphisms have only been studied in other neurodegenerative diseases such as Alzheimer’s disease and Parkinson’s disease but not in glaucoma." (PMID 33803434, 2021). "In addition, PGC-1α was shown to attenuate MPTP-induced neurodegenerative processes in a Parkinson’s disease (PD) model by upregulating mitochondrial antioxidants, such as GPx1 and SOD2, thereby reducing ROS production." (PMID 33771213, 2021). "Various studies with Gpx-1 transgenic mice suggest that this mediator may be neuroprotective against amyloid toxicity, Parkinsons-related pathologies, ischemia-reperfusion, or trauma." (PMID 23285140, 2012). "Previous studies have shown that GPX1 regulates oxidative stress and ERS-related apoptosis in Alzheimer’s disease and Parkinson’s disease." (PMID 40650067, 2025). "Among the most confident differentially abundant proteins (p ≤ 0.01), we found glutathione peroxidase 1 (GPX1), an important antioxidant enzymes that has already been described as protective in various neurodegenerative disorders, including Parkinson’s and Alzheimer’s disease." (PMID 36899835, 2023).
Alzheimer disease (8 papers, 2012 to 2025). A progressive, neurodegenerative disease characterized by loss of function and death of nerve cells in several areas of the brain leading to loss of cognitive function such as memory and language. "Further, existing research links GPX1 and SelenoW to risk for Alzheimer’s Disease (AD)." (PMID 36090351, 2022). "Overexpression of GPX enzymes such as GPX1 and GPX4 is thought to protect against neurodegenerative processes, including convulsive disorders, Alzheimer’s disease, and PD." (PMID 39273702, 2024).